TVP23C-CDRT4 (TVP23C-CDRT4 readthrough)
Synonyms: FAM18B2-CDRT4
Gene: Protein-coding gene on chromosome 17 (15,436,021 to 15,563,561, reverse strand). Ensembl gene ENSG00000259024.
Genetic constraint (gnomAD): Loss-of-function variants: 19 observed, 24.63 expected, observed/expected ratio (o/e) 0.77, 90% interval 0.54 to 1.13. The upper end of that interval is the gene's LOEUF score, 1.13, which puts it in group 4 of 6, group 1 being the genes least tolerant of losing a copy. Missense variants: 155 observed, 187.01 expected, observed/expected ratio (o/e) 0.83, 90% interval 0.73 to 0.95. Synonymous variants: 58 observed, 66.84 expected, observed/expected ratio (o/e) 0.87, 90% interval 0.7 to 1.08.